GNG5 (G protein subunit gamma 5)
Description:
Guanine nucleotide-binding proteins (G proteins) are involved as a modulator or transducer in various transmembrane signaling systems. The beta and gamma chains are required for the GTPase activity, for replacement of GDP by GTP, and for G protein-effector interaction.
Tractability: Antibody: UniProt places it where antibodies can reach, with high confidence; its Gene Ontology location is reachable by antibodies, with high confidence. PROTAC: ubiquitination databases record sites on it; its protein half-life has been measured.
Gene: Protein-coding gene on chromosome 1 (84,498,284 to 84,507,237, reverse strand). Ensembl gene ENSG00000174021.
Subcellular location: Cell membrane
Pathways (Reactome):
Signal Transduction: Ca2+ pathway; Extra-nuclear estrogen signaling; G alpha (12/13) signalling events; G alpha (i) signalling events; G alpha (q) signalling events; G alpha (s) signalling events; G alpha (z) signalling events; G beta:gamma signalling through BTK; G beta:gamma signalling through CDC42; G beta:gamma signalling through PI3Kgamma; G beta:gamma signalling through PLC beta; G-protein activation; GPER1 signaling; Glucagon-type ligand receptors
Hemostasis: ADP signalling through P2Y purinoceptor 1; ADP signalling through P2Y purinoceptor 12; Prostacyclin signalling through prostacyclin receptor; Thrombin signalling through proteinase activated receptors (PARs); Thromboxane signalling through TP receptor
Metabolism: Adrenaline,noradrenaline inhibits insulin secretion; Glucagon signaling in metabolic regulation; Glucagon-like Peptide-1 (GLP1) regulates insulin secretion
Neuronal System: Activation of G protein gated Potassium channels; Inhibition of voltage gated Ca2+ channels via Gbeta/gamma subunits; Presynaptic function of Kainate receptors
Cellular responses to stimuli: High laminar flow shear stress activates signaling by PIEZO1 and PECAM1:CDH5:KDR in endothelial cells
Disease: ADORA2B mediated anti-inflammatory cytokines production
Metabolism of proteins: Cooperation of PDCL (PhLP1) and TRiC/CCT in G-protein beta folding
Transport of small molecules: Vasopressin regulates renal water homeostasis via Aquaporins
Gene Ontology:
Molecular function: PDZ domain binding; protein binding; G-protein beta-subunit binding; GTPase activity
Biological process: G protein-coupled receptor signaling pathway; signal transduction
Cellular component: extracellular exosome; membrane; heterotrimeric G-protein complex; plasma membrane; G-protein beta/gamma-subunit complex
Genetic constraint (gnomAD): Loss-of-function variants: 0 observed, 1.67 expected, observed/expected ratio (o/e) 0, 90% interval 0 to 1.49. That is too few expected variants to judge how well the gene tolerates losing a copy. Missense variants: 33 observed, 27.2 expected, observed/expected ratio (o/e) 1.21, 90% interval 0.92 to 1.62. Synonymous variants: 13 observed, 10.01 expected, observed/expected ratio (o/e) 1.3, 90% interval 0.84 to 1.86.
Homologues: Orthologues: macaque GNG5 (100% identical), mouse Gng5 (100% identical), pig GNG5 (100% identical), rabbit GNG5 (100% identical), rat Gng5 (100% identical), dog GNG5 (93% identical), zebrafish gng5 (84% identical), Drosophila melanogaster Ggamma1 (35% identical). Paralogues in human: GNG5B (94% identical), GNG10 (53% identical), GNG2 (49% identical), GNG3 (49% identical), GNG12 (47% identical), GNG4 (47% identical), GNG7 (47% identical), GNG8 (44% identical), GNG11 (29% identical), GNGT2 (29% identical), GNGT1 (26% identical).
Diseases named in the same sentence as GNG5 in open-access papers:
GNG5 is named in the same sentence as 43 diseases in open-access papers, as found by Europe PMC text mining. Sharing a sentence is not in itself a finding about the gene and the disease. The quoted sentences say what the papers report.
glioma (14 papers, 2020 to 2025). A benign or malignant brain and spinal cord tumor that arises from glial cells (astrocytes, oligodendrocytes, ependymal cells). "Previous studies have implicated GNG5 in glioma cell proliferation, migration, and macrophage infiltration." (PMID 40433374, 2025). "Results from univariate and multivariate analyses showed that increased expression of GNG5 is an independent risk factor for glioma patients." (PMID 34098960, 2021). "In this study, a subtype‐associated independent prognosis factor, GNG5, was identified in gliomas by using an integrated bioinformatics method and served as an important role in glioma pathogenesis." (PMID 33000557, 2020). "Taken together, these results reveal that GNG5 expression is strongly associated with a poor prognosis and serves an independent prognostic factor of OS for gliomas." (PMID 33000557, 2020). "Collectively, these findings indicate that overexpressed GNG5 is associated clinicopathological characteristics of glioma patients." (PMID 33000557, 2020). "Together, we believe that the signaling pathways enriched with GNG5 in glioma, as revealed in our study, could provide the basis for further investigations into the specific mechanisms underlying GNG5 functioning in glioma." (PMID 34098960, 2021). "Overexpression of GNG5 was associated with pool prognosis in patients with glioma." (PMID 34222011, 2021). "The results show that increased expression of GNG5 could indeed cause a poor prognosis of glioma patients." (PMID 34098960, 2021). "Furthermore, we found that GNG5 expression levels are closely related to the clinical features associated with glioma prognosis, especially with the pathological grade and primary recurrence status of glioma." (PMID 34098960, 2021). "In addition, GNG5 expression was strongly related to important molecular characteristics of gliomas, such as IDH mutation and 1p/19q codeletion status in CGGA mRNA‐array_301." (PMID 33000557, 2020). "In conclusion, this study demonstrated that GNG5 was overexpressed in gliomas and significantly associated with clinicopathologic characteristics and molecular subtypes, suggesting that it was a subtype‐associated gene in the molecular classification of gliomas." (PMID 33000557, 2020). "Overall, GNG5 expression is closely associated with clinicopathologic characteristics and is an independent prognostic indicator for glioma patients, as well as a promising subtype‐associated biomarker in molecular classification of gliomas." (PMID 33000557, 2020). "Likewise, our study showed that GNG5 expression was down‐regulated in gliomas with IDH mutation and glioma patients with low GNG5 expression had a longer OS time compared with the high GNG5 expression group." (PMID 33000557, 2020). "Gliomas overexpress the oncogene GNG5, which can prevent glioma cells from proliferating and migrating, resulting in a poor prognosis." (PMID 40594780, 2025). "Zhang and Yang found that GNG5 was an unfavorable prognostic factor in glioma, and it can promote the proliferation and migration of glioma cells." (PMID 37239411, 2023). "Patients with glioma exhibiting elevated GNG5 expression have a shorter survival time, and patients with head and neck squamous cell carcinoma and elevated PRELID2 expression have a poor prognosis." (PMID 35968507, 2022). "Among the positively correlated genes, evidence shows that GNG5, HMGB2, PCNA and HSPB11 can induce the proliferation and metastasis of glioma, causing poor prognosis and reducing the OS of patients with glioma." (PMID 34953037, 2022). "The results suggest that GNG5 is correlated with the infiltration abundance of various immune cells in glioma, especially macrophage, dendritic cells, and neutrophils in low-grade glioma." (PMID 34098960, 2021). "Taken together, these results indicate that a correlation exists between GNG5 expression and the molecular and clinical characteristics of glioma." (PMID 34098960, 2021).
glioma (continued). "The results showed that high expression of GNG5 is significantly correlated with reduced survival of glioma patients (P < 0.001); these results were verified based on TCGA database and GSE53733 dataset." (PMID 34098960, 2021). "Our study shows that GNG5 is highly expressed in gliomas, and this expression is correlated with various molecular and clinical features of glioma patients." (PMID 34098960, 2021). "Together, these results further indirectly reveal that the expression of GNG5 correlates with the prognosis of glioma patients." (PMID 34098960, 2021). "The ssGSEA, ESTIMATE, and TIMER based analysis indicated a correlation between GNG5 expression and various immune cells in glioma." (PMID 34098960, 2021). "And the results showed that GNG5 expression was significantly higher in gliomas relative to normal brain tissue (P < 0.001), which was consistent with the results of RT-qPCR (P < 0.05)." (PMID 34098960, 2021). "RT-qPCR results showed that the expression level of GNG5 in many kinds of glioma cells was significantly higher than that in HA cells." (PMID 34098960, 2021). "First, as extensive clinical sample information in the public databases is not always available, it is difficult to comprehensively evaluate the correlation between GNG5 and the clinical features of glioma patients." (PMID 34098960, 2021). "We used data on more than a thousand gliomas from multiple databases and clinical data to determine the expression of GNG5 in glioma." (PMID 34098960, 2021). "GSEA revealed the potential signaling pathways involved in GNG5 function in gliomas, including cell adhesion molecules signaling pathway." (PMID 34098960, 2021). "Analysis of follow-up results of 40 glioma patients showed that patients with high expression of GNG5 had shorter OS (P < 0.05), and this result was confirmed in multiple datasets containing large samples." (PMID 34098960, 2021). "In order to study the function of GNG5 in glioma cells in vitro and in vivo, we knocked down the expression level of GNG5 in glioma cells by cell transfection technology." (PMID 34098960, 2021). "We found that knockdown of the expression level of GNG5 significantly reduced the metastatic and proliferative abilities of glioma cells." (PMID 34098960, 2021). "The results indicated that the GNG5 expression level in gliomas was significantly correlated with the pathological grade and the age of the patients (P < 0.001)." (PMID 34098960, 2021). "In our study, we found that the expression of VCAM1, ICAM1, CDH2 was down-regulated, while the expression of SDC2 was up-regulated after knocking down the expression of GNG5 in glioma cells." (PMID 34098960, 2021). "The average level of GNG5 expression in tissue from patients with recurrent gliomas was higher than in patients with primary and secondary tumors (P < 0.001)." (PMID 34098960, 2021). "To elucidate in large sample data that GNG5 is an oncogene and can lead to a poorer prognosis for patients, we obtained clinical information on more than a thousand glioma samples from TCGA, CGGA, and GEO databases." (PMID 34098960, 2021). "Although we used bioinformatics analysis and large datasets to uncover the role of GNG5 in glioma, our study has a few limitations." (PMID 34098960, 2021). "The overexpression of Gng5 has been related to apoptosis in adenocarcinoma and invasive ductal carcinoma and is considered to be a prognostic indicator of gliomas." (PMID 34445296, 2021). "GNG5 is highly expressed in gliomas, and its expression level is positively correlated with pathological grade, histological type, age, and tumor recurrence and negatively correlated with isocitrate dehydrogenase mutation, 1p/19 co-deletion, and chemotherapy." (PMID 34098960, 2021). "Our results showed that GNG5 expression was increased in glioma based on data from sequencing, microarrays, and qPCR data." (PMID 34098960, 2021).
glioma (continued). "Taken together, GNG5 is associated with clinical features and acts an independent prognostic indicator of OS in gliomas, suggesting that GNG5 might play a critical role in tumorigenesis and be a potential gene of diagnosis, treatment and prognosis for glioma patients." (PMID 33000557, 2020). "According to the median of GNG5 expression, glioma samples were divided into two groups: low GNG5 expression group and high GNG5 expression group." (PMID 33000557, 2020). "Subsequently, survival analyses showed that gliomas with GNG5 overexpression had shorter OS and DFS time compared with low GNG5 gliomas." (PMID 33000557, 2020). "GNG5 in gliomas was overexpressed compared with normal samples and associated with clinicopathologic characteristics." (PMID 33000557, 2020). "The survival result in explicitly illustrated that 39 gliomas with GNG5 overexpression have shorter overall survival compared with the 38 samples with GNG5 low expression (P = .016)." (PMID 33000557, 2020). "Survival and Cox regression analyses showed that glioma patients with GNG5 overexpression had shorter survival time, and GNG5 was an independent prognostic indicator of overall survival." (PMID 33000557, 2020). "High expression of GNG5 was relevant to unfavorable prognosis in gliomas." (PMID 35503998, 2022). "Our results suggest that GNG5 may participate in the malignant progression of glioma through ECM-receptor interaction, toll-like receptor pathway, and the nod-like receptor signaling pathways, which are reported to be related to the immune response process." (PMID 34098960, 2021). "Therefore we are more confident that GNG5 can exert its biological effects by regulating different signaling pathways including cell adhesion molecules in glioma." (PMID 34098960, 2021). "Therefore, we aimed to identify the relationship between GNG5 and glioma prognosis and identify a new biomarker for the diagnosis and treatment of gliomas." (PMID 34098960, 2021). "GSEA was used to identify GNG5 related signaling pathways involved in gliomas." (PMID 34098960, 2021). "Furthermore, we used data from the CGGA database that contains a large number of glioma gene expression profiles and a vast amount of clinical information data to further analyze the relationship between GNG5 expression and the clinical features of glioma." (PMID 34098960, 2021). "We found that decreasing the expression level of GNG5 in glioma cells could significantly affect the expression of VCAM1, ICAM1, CDH2, and SDC2, which are key molecules of cell adhesion molecules." (PMID 34098960, 2021). "The results showed that the expression of GNG5 in glioma was correlated with immune activity." (PMID 34098960, 2021). "Moreover, we validated the expression pattern of GNG5 protein in glioma samples obtained from clinic and HPA databases, and a high level of GNG5 was observed in glioma." (PMID 34098960, 2021). "However, the mechanism explaining how GNG5 leads to a poor prognosis for glioma patients is yet to be elucidated." (PMID 34098960, 2021). "In vivo and in vitro experiments showed that GNG5 could participate in glioma cell proliferation and migration." (PMID 34098960, 2021). "To clarify the correlation between highly expressed GNG5 in gliomas and clinicopathological features, we first analyzed the clinicopathological information of 40 glioma patients and found that the expression level of GNG5 was significantly correlated with the pathological grade of gliomas." (PMID 34098960, 2021). "Functional experiments were performed to explore the function of GNG5 in glioma cells." (PMID 34098960, 2021). "To further understand the role of GNG5 in tumors, we focused on its role in glioma." (PMID 34098960, 2021). "The results of in vivo and in vitro experiments indicated that GNG5 could participate in the malignant progression of gliomas by participating in the proliferation and migration of gliomas." (PMID 34098960, 2021).
glioma (continued). "Although the high expression of GNG5 in glioma could reduce patients' OS rate, whether the expression of GNG5 is necessarily correlated with such a prognosis for glioma patients was further examined." (PMID 34098960, 2021). "High expression levels of GNG5 predict a poor prognosis in glioma patients." (PMID 34098960, 2021). "We found that GNG5 was significantly highly expressed in a variety of cancers, including gliomas." (PMID 34098960, 2021). "Decreasing the expression of GNG5 can inhibit glioma cell proliferation and migration." (PMID 34098960, 2021). "We next undertook a GSEA to understand the functioning of GNG5 in glioma." (PMID 34098960, 2021). "GNG5 was also found to serve as an independent prognostic indicator for glioma patients." (PMID 33000557, 2020). "Therefore, GNG5 was selected a potential signature gene in glioma diagnosis and prognosis for the next analyses." (PMID 33000557, 2020). "Second, through comprehensive biological analysis, we found that GNG5 may be involved in a variety of biological processes to affect the prognosis of gliomas, although the in vitro and in vivo experiments involved in this study are only preliminary verification." (PMID 34098960, 2021). "Thus, GNG5 expression is correlated with various genes in gliomas." (PMID 34098960, 2021). "Moreover, subcutaneous tumorigenesis experiments showed that downregulation of GNG5 could significantly inhibit the growth of glioma tissues (P < 0.05)." (PMID 34098960, 2021). "Additionally, GNG5 may participate in glioma's pathological progress through the signaling pathways related to cancer, such as cell adhesion molecules signaling pathway." (PMID 34098960, 2021). "Thus, GNG5 is a potential novel biomarker for the clinical diagnosis and treatment of gliomas." (PMID 34098960, 2021). "Moreover, our follow-up results suggested that GNG5 highly expressed in gliomas could significantly decrease patients' OS." (PMID 34098960, 2021). "Furthermore, IHC staining results based on clinical samples showed that the expression level of GNG5 in gliomas was significantly higher than that in control groups and higher in high-grade gliomas than in low-grade gliomas, and this result was also confirmed in the HPA database." (PMID 34098960, 2021). "Furthermore, to visualize the association between GNG5 expression and IDH mutation in clinical samples, we performed IHC staining on clinical samples, which showed a significant correlation between IDH mutation and GNG5 expression levels in gliomas." (PMID 34098960, 2021). "Therefore, our results indicate that GNG5 may serve as a biomarker for glioma patients, especially for the 5-year OS group." (PMID 34098960, 2021). "Furthermore, ROC analysis showed that GNG5 could be an effective potential signature gene of diagnosis prediction between glioma and normal samples in GSE4290 (AUC = 0.870)." (PMID 33000557, 2020). "Similarly, glioma patients with 1p/19q codeletion carried an IDH mutation, and in our study that glioma patients carrying 1p/19q codeletion had a lower expression level of GNG5." (PMID 33000557, 2020). "These suggested that GNG5 might regulate glioma growth by activating PI3K/Akt signalling pathway." (PMID 33000557, 2020). "It should also be noted that the function of KCNC1, KCNT1, RIMS2, NECAP2, GNG5, SCAMP2, GNAI3 genes is also correlated with membrane function in low-grade gliomas." (PMID 37239411, 2023). "Therefore, we hypothesized that GNG5 might be an oncogene in glioma." (PMID 34098960, 2021). "However, the association of GNG5 with glioma immunity has not been reported." (PMID 34098960, 2021). "Therefore, we hypothesized that GNG5 might be involved in the immune response in glioma." (PMID 34098960, 2021). "The mRNA expression of APOBEC3C, FCGRT, GNG5, and SP100 was elevated in glioma, whereas the expression of ADAP2, ALOX5AP, and LRRC25 was low." (PMID 32431729, 2020). "Thus, GNG5 might be a potential gene of molecular classification in gliomas." (PMID 33000557, 2020).